CYCSP40 (CYCS pseudogene 40)
Synonyms: HCP40; HC7
Gene: Processed pseudogene on chromosome 17 (77,198,950 to 77,199,543, reverse strand). Ensembl gene ENSG00000262870.
Diseases named in the same sentence as CYCSP40 in open-access papers:
CYCSP40 is named in the same sentence as 3 diseases in open-access papers, as found by Europe PMC text mining. Sharing a sentence is not in itself a finding about the gene and the disease.
CYCSP40 shares sentences with these, for which no sentence is quoted: breast carcinoma (1 paper); cancer (1); tumor (1).